KIDINS220 (kinase D interacting substrate 220)
Description:
Promotes a prolonged MAP-kinase signaling by neurotrophins through activation of a Rap1-dependent mechanism. Provides a docking site for the CRKL-C3G complex, resulting in Rap1-dependent sustained ERK activation. May play an important role in regulating postsynaptic signal transduction through the syntrophin-mediated localization of receptor tyrosine kinases such as EPHA4. In cooperation with SNTA1 can enhance EPHA4-induced JAK/STAT activation. Plays a role in nerve growth factor (NGF)-induced recruitment of RAPGEF2 to late endosomes and neurite outgrowth. May play a role in neurotrophin- and ephrin-mediated neuronal outgrowth and in axon guidance during neural development and in neuronal regeneration (By similarity). Modulates stress-induced apoptosis of melanoma cells via regulation of the MEK/ERK signaling pathway.
Synonyms: ARMS; SINO; VENARG
Tractability: Antibody: UniProt predicts a signal peptide or a membrane-spanning region. PROTAC: ubiquitination databases record sites on it; its protein half-life has been measured.
Gene: Protein-coding gene on chromosome 2 (8,721,081 to 8,837,630, reverse strand). Ensembl gene ENSG00000134313.
Subcellular location: Membrane; Late endosome
Subcellular location (Human Protein Atlas): Nucleoplasm; Cytosol; Vesicles
Pathways (Reactome):
Signal Transduction: ARMS-mediated activation; RND1 GTPase cycle; RND2 GTPase cycle
Gene Ontology:
Molecular function: protein binding; PDZ domain binding; protein kinase regulator activity
Biological process: cellular response to nerve growth factor stimulus; nerve growth factor signaling pathway; positive regulation of neuron projection development
Cellular component: membrane; cytosol; late endosome; protein-containing complex; synapse
Genetic constraint (gnomAD): Loss-of-function variants: 37 observed, 107.58 expected, observed/expected ratio (o/e) 0.34, 90% interval 0.26 to 0.45. The upper end of that interval is the gene's LOEUF score, 0.45, which puts it in group 2 of 6, group 1 being the genes least tolerant of losing a copy. Missense variants: 1,459 observed, 1,883.6 expected, observed/expected ratio (o/e) 0.77, 90% interval 0.74 to 0.81. Synonymous variants: 621 observed, 695.46 expected, observed/expected ratio (o/e) 0.89, 90% interval 0.83 to 0.95.
Gene-disease validity (ClinGen):
ClinGen rates the evidence that KIDINS220 causes each of these diseases.
ventriculomegaly and arthrogryposis (autosomal recessive): Definitive.
spastic paraplegia, intellectual disability, nystagmus, and obesity (autosomal dominant): Moderate.
Homologues: Orthologues: chimpanzee KIDINS220 (99% identical), pig KIDINS220 (95% identical), rat Kidins220 (94% identical), macaque KIDINS220 (94% identical), mouse Kidins220 (93% identical), dog KIDINS220 (93% identical), rabbit KIDINS220 (92% identical), guinea pig KIDINS220 (90% identical), tropical clawed frog kidins220 (80% identical), zebrafish kidins220b (70% identical), zebrafish kidins220a (67% identical).
Diseases named in the same sentence as KIDINS220 in open-access papers:
KIDINS220 is named in the same sentence as 61 diseases in open-access papers, as found by Europe PMC text mining. Sharing a sentence is not in itself a finding about the gene and the disease. The quoted sentences say what the papers report.
Spastic paraplegia (10 papers, 2020 to 2025). Complete loss of the ability to move the lower limbs accompanied by spasticity of the lower limbs. "Variants in the KIDINS220 gene cause a spectrum of disorders such as AD spastic paraplegia, intellectual disability, nystagmus, and obesity (SINO) syndrome; AR ventriculomegaly; and arthrogryposis." (PMID 41153514, 2025). "Mutations in the human KIDINS220 gene are associated with a neurodevelopmental disorder (‘SINO’ syndrome) characterized by spastic paraplegia, intellectual disability, and in some cases, autism spectrum disorder." (PMID 38397009, 2024). "De novo loss-of-function variants involving the last 2 exons (29 and 30) of KIDINS220 have been associated with spastic paraplegia, intellectual disability, nystagmus, and obesity (SINO) (OMIM #617296)." (PMID 39495751, 2024). "Previously de novo nonsense variants in KIDINS220 were observed in patients with spastic paraplegia, intellectual disability, nystagmus, and obesity (SINO) syndrome." (PMID 39109120, 2024). "Four heterozygous KIDINS220 pathogenic variants have been reported in as many sporadic patients affected by spastic paraplegia (SP), intellectual disability (ID), and obesity." (PMID 39336781, 2024). "A few terminal truncating variants in KIDINS220 cause spastic paraplegia (SP), intellectual disability (ID), nystagmus, and obesity (SINO, MIM #617296)." (PMID 39336781, 2024). "Nonsense variants in KIDINS220/ARMS were identified as the main cause of spastic paraplegia, intellectual disability, nystagmus, and obesity (SINO) syndrome, a rare disease with birth defects in brachycephaly, neurological disorder, and obesity." (PMID 33763417, 2021). "Kinase D interacting substrate of 220 kDa (KIDINS220) gene has been recently associated with schizophrenia and with a novel syndrome characterized by spastic paraplegia, intellectual disability, nystagmus and obesity (SINO syndrome), diseases frequently occurring with ventriculomegaly." (PMID 34002021, 2021). "KIDINS220 heterozygous nonsense variants have been recently associated with SINO syndrome, a novel rare autosomal disease characterized by spastic paraplegia, intellectual disability, nystagmus and obesity in children." (PMID 34002021, 2021). "More recently, KIDINS220 nonsense and loss-of-function variants have been associated with SINO syndrome, a novel rare autosomal disease characterized by spastic paraplegia, intellectual disability, nystagmus and obesity, signs that concur with different degrees of ventriculomegaly." (PMID 34002021, 2021). "The symptoms of spastic paraplegia, intellectual disability, and nystagmus could be explained by the key roles of KINDIS220/ARMS in neuronal cell survival, differentiation, and synaptic modulation, but how the truncated KIDINS220/ARMS causes severe obesity remains unclear." (PMID 33763417, 2021). "Patient 91 with c.850del in the KIDINS220 gene (NM_020738.2) showed failure to thrive, microcephaly, global developmental delay, mild dysmorphism, that is, not consistent with phenotype of Spastic paraplegia, intellectual disability, nystagmus, and obesity." (PMID 32901917, 2020).
Intellectual disability (9 papers, 2020 to 2025). "This case broadens the clinical spectrum of KIDINS220 variant-related disorders to encompass HSP with intellectual disability." (PMID 41153514, 2025). "Case 8 was the first Turkish patient with the KIDINS220 gene, thus broadening the clinical spectrum of KIDINS220 variation-related disorders to encompass HSP with intellectual disability without nystagmus and obesity." (PMID 41153514, 2025).
Obesity (9 papers, 2020 to 2025). Accumulation of substantial excess body fat. "Although truncating and missense variants in KIDINS220 have been observed in individuals with obesity, the gene-disease relationship remains inconclusive." (PMID 41333852, 2025). "The cause of neural cell dysfunction by KIDINS220/ARMS were extensively studied while the cause of obesity in SINO syndrome remains elusive." (PMID 33763417, 2021). "To elucidate the possible functions of KIDINS220/ARMS in adipose cell that might cause obesity, we studied the mechanisms of KIDINS220/ARMS in the adipogenic differentiation process." (PMID 33763417, 2021). "Also, while variants of uncertain significance in KIDINS220 and POMC were identified, their clinical contribution remains uncertain; ongoing monitoring is warranted given reported associations of POMC variants with obesity and of KIDINS220 variants with neurodevelopmental features." (PMID 41333852, 2025). "However, why nonsense mutations of KIDINS220/ARMS lead to obesity remains unknown and warrants further investigation." (PMID 33763417, 2021). "To address whether KIDINS220/ARMS had functions in adipocyte differentiation, which was critical to the onset of obesity in childhood, we examined the expression level of KINDIS220/ARMS during adipocyte maturation." (PMID 33763417, 2021). "Obesity is also a remarkable symptom of SINO patients, but whether it is caused by KIDINS220/ARMS dysfunction in fat metabolism and adipocytes regulation, or due to impaired movement ability and more food intake remains unclear." (PMID 33763417, 2021). "KIDINS220/ARMS could function as a negative regulator in adipocyte differentiation and maturation via sustained ERK signaling, thus the truncated mutation of KIDINS220/ARMS could prompt adipocyte maturation and leads to obesity." (PMID 33763417, 2021). "Interestingly, obesity was also found in almost all SINO patients; however, it is not clear whether obesity of SINO patients is caused by KIDINS220/ARMS dysfunction or due to impaired movement ability." (PMID 33763417, 2021). "Here, to elucidate the possible functions of KIDINS220/ARMS in the pathogenesis of obesity, we examined the role of KIDINS220/ARMS in preadipocyte differentiation." (PMID 33763417, 2021). "The truncated form of KIDINS220/ARMS found in SINO patients might lose its biological functions in controlling adipocyte differentiation, thus leading to uncontrolled adipocyte maturation, lipid accumulation, and obesity." (PMID 33763417, 2021).
Hydrocephalus (4 papers, 2021 to 2024). Hydrocephalus is an active distension of the ventricular system of the brain resulting from inadequate passage of CSF from its point of production within the cerebral ventricles to its point of absorption into the systemic circulation. "Homozygous KIDINS220 pathogenic variants inherited from healthy parents were reported to be lethal in fetuses due to either severe progressive hydrocephalus within the twentieth gestational week or congenital heart disease and hydrops fetalis." (PMID 39336781, 2024). "Our data call for further investigations on the SEZ in Kidins220-deficient mice afflicted with severe hydrocephalus, as future follow-up for this work." (PMID 37542079, 2023). "Kidins220-deficient mice present hydrocephalus, and because previous reports have linked reduced SEZ NSCs numbers to this condition in vivo, we have only investigated mice with moderate enlargement of the ventricles in this study." (PMID 37542079, 2023). "Together, these data indicate that Kidins220f/f mice constitute a hypomorphic model with marked deficiency of Kidins220 in several tissues, supporting the notion that the decrease of Kidins220 brain levels is linked to ventriculomegaly and hydrocephalus development." (PMID 34002021, 2021). "Kidins220 has been recently involved in the etiopathology of hydrocephalus, as Kidins220f/f mice present ventriculomegaly at different degrees." (PMID 37542079, 2023). "Here we identify Kidins220 as a key determinant in the control of brain water homeostasis, ventricular enlargement and hydrocephalus pathology by molecular mechanisms that involve the unexpected expression regulation of SNX27-retromer components, which in turn controls AQP4 turnover." (PMID 34002021, 2021).
melanoma (4 papers, 2011 to 2021). A malignant, usually aggressive tumor composed of atypical, neoplastic melanocytes. "Kidins220 overexpression has been reported in melanoma and it has been shown to contribute to tumor formation by activating MEK/ERK signaling pathway and consequently preventing transformed melanocytes from the stress-induced apoptosis." (PMID 27329728, 2016). "Accumulated evidences have indicated that KIDINS220/ARMS could phosphorylate and sustain ERK signaling in different types of cells, such as neurons, lymphocytes, and melanoma cells." (PMID 33763417, 2021).
Ventriculomegaly (4 papers, 2021 to 2025). An increase in size of the ventricular system of the brain. "We also find that Kidins220 deficient mice develop ventriculomegaly accompanied by water dyshomeostasis and loss of AQP4 in the brain ventricular ependymal layer and astrocytes." (PMID 34002021, 2021). "In addition, rare novel missense variants in KIDINS220 gene have been associated with schizophrenia, a psychiatric disorder with a strong linkage to ventriculomegaly." (PMID 34002021, 2021). "This phenotype is relevant as human fetuses bearing loss-of-function Kidins220 mutations and children affected by SINO display ventriculomegaly." (PMID 35140204, 2022). "The Kidins220 hypomorphic mouse model shows various degrees of Kidins220 downregulation that positively correlate with ventriculomegaly penetrance." (PMID 34002021, 2021). "Our data suggest that the milder presentations of ventriculomegaly do not affect SEZ NSCs and progeny, at least in our Kidins220-deficient mice models and at the age studied." (PMID 37542079, 2023).
Alzheimer disease (3 papers, 2021 to 2024). A progressive, neurodegenerative disease characterized by loss of function and death of nerve cells in several areas of the brain leading to loss of cognitive function such as memory and language. "Consistently, failure to properly regulate GSK3 activity plays a role in Alzheimer’s disease and schizophrenia, diseases associated with Kidins220 alterations, amongst others." (PMID 37542079, 2023). "KIDINS220 expression is altered in cancer and in neurological and neurodegenerative disorders, including cerebral ischemia, Alzheimer’s disease, Huntington ́s disease and idiopathic normal pressure hydrocephalus." (PMID 37542079, 2023). "In addition to its functions in cellular biology and development, growing evidences have also linked KIDINS220/ARMS to different pathologies of human diseases, including Alzheimer’s disease (AD), asthma, and cancer." (PMID 33763417, 2021).
prostate carcinoma (3 papers, 2016 to 2020). A carcinoma that arises from epithelial cells of the prostate gland. "Loss of miR-4638-5p promotes VM in castration resistant prostate cancer by activating PI3K/AKT signaling via the kinase D-interacting substrate of 220 kDa (KIDINS220) scaffold protein." (PMID 29112161, 2017). "miR-4638-5p was reported to influence prostate cancer progression via angiogenesis by regulating Kidins220 as well as the downstream activity of the PI3K/AKT and VEGF pathways." (PMID 33182754, 2020). "Furthermore, we found that miR-4638-5p, through regulating Kidins220 and the downstream activity of VEGF and PI3K/AKT pathway, influences prostate cancer progression via angiogenesis." (PMID 27329728, 2016).
Cerebral ischemia (2 papers, 2015). Restriction of arterial blood supply to the brain associated with insufficient oxygenation to support the metabolic requirements of the tissue. "In the case of Kidins220/ARMS, overactivation of NMDARs in excitotoxicity and cerebral ischemia triggers its downregulation, which contributes to neuronal death." (PMID 26492372, 2015).
cognitive decline (2 papers, 2020 to 2023). "The data presented herein point to the possibility that alterations in KIDINS220 could render the DG neurogenic niche more sensitive to cognitive decline, and memory and learning disabilities, traits associated with these diseases." (PMID 37542079, 2023).
hereditary spastic paraplegia (2 papers, 2024 to 2025). Hereditary spastic paraplegias (HSP) comprise a genetically and clinically heterogeneous group of neurodegenerative disorders characterized by progressive spasticity and hyperreflexia of the lower limbs. "This case presents a somewhat unique and different phenotype of hereditary spastic paraplegia from previously reported kinase D-interacting substrate of 220 kDa (KIDINS220) gene mutation-related disease." (PMID 39109120, 2024). "We report a unique putative causative heterozygous mutation in KIDINS220 in a pure hereditary spastic paraplegia (HSP) patient expanding the HSP group further." (PMID 39109120, 2024). "Mutations in KIDINS220 are known to cause hereditary spastic paraplegia (HSP) and SINO syndrome." (PMID 41164410, 2025).
neuropathies (2 papers, 2020 to 2023). "At least TUBGCP6, SYNE1, BPTF, KIDINS220, MYO5A, VPS13B, TBC1D24) are known to contain mutations causing various neuropathies." (PMID 32561887, 2020).
Anxiety (1 paper, 2022). Intense feelings of nervousness, tension, or panic often arise in response to interpersonal stresses. "The deletion of Kidins220 leads to behavioral changes, such as reduced anxiety-like traits linked to alterations in TrkB-BDNF signaling and sex-dependent alterations of hippocampal-dependent spatial memory." (PMID 35140204, 2022). "We compared Kidins220lox/lox and Kidins220 cKO animals and identified changes of brain neuron morphology and reduced anxiety, partially ascribable to impairments of the BDNF/TrkB axis." (PMID 35140204, 2022). "Kidins220lox/lox and +/+ animals showed comparable performances in both open field and elevated plus maze tests with no gender differences, indicating that the anxiety-like phenotypes were attributable to the deletion of Kidins220." (PMID 35140204, 2022).
brain malformations (1 paper, 2024). "The patient reported here widens the spectrum of the brain malformations/dysmorphisms, which demonstrates that accurate neuroimaging in childhood and at follow-up seems crucial in detecting the complexity of brain malformations associated with KIDINS220 pathogenic variants." (PMID 39336781, 2024).
congenital hydrocephalus (1 paper, 2021). Hydrocephalus that is present at birth. "Due to the importance of the ventricular ependyma in brain water homeostasis and congenital hydrocephalus, we examined the presence of Kidins220 in this specialised tissue by using a recently generated antibody." (PMID 34002021, 2021).
depression (1 paper, 2012). "Importantly, our study unveiled specific differences in the response to paired-pulse stimulation and in the recovery from train-induced depression, in line with a novel role of Kidins220 in GABAergic short-term plasticity." (PMID 22563401, 2012).
glioma (1 paper, 2023). A benign or malignant brain and spinal cord tumor that arises from glial cells (astrocytes, oligodendrocytes, ependymal cells). "Additionally, in pediatric high-grade glioma copy number breakpoint within KIDINS220 gene have been identified." (PMID 37542079, 2023). "Whether KIDINS220 could be part of the stimulus-response threshold activating this pro-survival pathway downstream of EGFR in glioma stem cells and possible therapeutic implications, deserves further investigation." (PMID 37542079, 2023).
Lissencephaly (1 paper, 2024). A spectrum of malformations of cortical development caused by insufficient neuronal migration that subsumes the terms agyria, pachygyria and subcortical band heterotopia. "Cerebellar involvement was detected in two prenatal cases and a baby girl with bi-allelic KIDINS220 pathogenetic variants, whereas lissencephaly, another feature of tubulinopathies, was reported in a further prenatal case; see." (PMID 39336781, 2024).
myopia (1 paper, 2024). "In one (1/18) child, we found genetic variants defined as VUS, and in four (4/18) children, we found (likely) pathogenic variants in the genes TRPV4, TUBA1A, SBDS, KIDINS220, which have not been previously associated with the development of myopia." (PMID 39495751, 2024). "It is also worth noting that our study describes cases of HM in individuals with variants in genes that have not yet been clearly associated with the development of myopia (TRPV4, TUBA1A, SBDS, KIDINS220)." (PMID 39495751, 2024).
neuroblastoma (1 paper, 2016). Neuroblastoma (NB) is the most common solid, extracranial childhood tumor. "Expression of Kidins220 has also been reported in neuroblastoma tumours, where it stabilizes nerve growth factor-induced survival signalling through MAPK/ERK signalling." (PMID 27329728, 2016).